PDE10A (phosphodiesterase 10A)
Diseases named in the same sentence as PDE10A in open-access papers (continued):
Sharing a sentence is not in itself a finding about the gene and the disease.
ischemic stroke (1 paper, 2015). A stroke disorder caused by obstruction of blood flow to the brain, due to thrombotic (local blood clot formation) or embolic (due to a blood clot or other material traveling from another site) event. "Among the downregulated genes, Gpr88, Rgs9, Enthd1, Olr59, P2ry12, Degs2, Pde10a, Neu2, Adora2a, and Slc22a6 were found to demonstrate significant downregulation in pathological phase of ischemic stroke." (PMID 25861363, 2015).
kidney tumor (1 paper, 2023). "In a kidney tumor, we identify 924 DCI genes involved in cell-type-specific functions such as PDE10A in tumor cells and CCL3 in lymphocytes." (PMID 37433798, 2023).
lung disease (1 paper, 2011). "Although the specific functional role of PDE10A in lung tissue needs to be characterized in more detail, the present study also suggests a reactivation of PDE10A signaling in abnormal proliferative lung disease tissues, such as the tissues observed in pathological vascular remodeling." (PMID 21494592, 2011).
metastatic disease (1 paper, 2025). "Furthermore, decreased PDE10A expression is associated with an EMT phenotype and metastatic disease in colon adenocarcinoma." (PMID 41179677, 2025). "-Loss of PDE10A associated with EMT transcriptional state and metastatic disease." (PMID 41179677, 2025).
microscopic polyangiitis (1 paper, 2023). Microscopic polyangiitis (MPA) is an inflammatory, necrotizing, systemic vasculitis that affects predominantly small vessels (i.e. small arteries, arterioles, capillaries, venules) in multiple organs. "Phosphodiesterase 10A antibody; Takayasu vasculitis; Rasmussen syndrome; celiac disease with anti-gliadin antibodies; steroid responsive Encephalopathy in Autoimmune Thyroiditis (SREAT); Microscopic polyangiitis (MPA)." (PMID 37993913, 2023).
myopia (1 paper, 2020). "The role of AREG and PDE10A in the pathogenesis of myopia requires further studies in animal models and human genetic epidemiology." (PMID 32269590, 2020). "However, elucidating the role of AREG and PDE10A in the pathogenesis of myopia requires further animal model and human genetic epidemiology studies." (PMID 32269590, 2020).
myxoma (1 paper, 2024). A benign soft tissue neoplasm characterized by the presence of spindle and stellate cells, lobulated growth pattern, and myxoid stroma formation. "One of the most notable findings was significant upregulation of cyclic nucleotide phosphodiesterase (PDE) gene families, including PDE3A, PDE1A, PDE7B, and PDE10A in myxoma cells." (PMID 39090109, 2024).
nicotine addiction (1 paper, 2021). "PDE2A and PDE10A, the two proteins comprising the morphine addiction KEGG pathway that was upregulated in male VTA after chronic nicotine and withdrawal, can modulate dopaminergic signaling but have not been linked to nicotine addiction directly." (PMID 34335180, 2021).
oral cancer (1 paper, 2019). "Glycolytic enzymes Aldoa, Hk2, Tpi1, Pgam2, Pfkl, and Pkm2 as well as the PKA-AMPK pathway genes Prkaa2, Pde4a, Pde10a, Ywhag, and Crebbp were downregulated by BRBs during oral cancer chemoprevention." (PMID 31336728, 2019).
ovarian serous adenocarcinoma (1 paper, 2022). An adenocarcinoma that arises from the ovary and is characterized by the presence of malignant epithelial cells that, in well differentiated tumors, resemble the epithelium of the fallopian tube or, in poorly differentiated tumors, show anaplastic features and marked nuclear atypia. "We analyzed The Cancer Genome Atlas (TCGA) ovarian serous adenocarcinomas data to investigate clinical-pathological features associated with PDE10A." (PMID 36324187, 2022).
ovarian tumors (1 paper, 2022). "Analysis of The Cancer Genome Atlas (TCGA) ovarian tumors revealed PDE10A overexpression was associated with significantly worse overall survival for patients." (PMID 36324187, 2022). "Somatic mutations in PDE10A were rare (3 out 606 samples), and 65.6% of the ovarian tumors showed decreased DNA copy number for PDE10A." (PMID 36324187, 2022). "We also aimed to investigate the molecular pathways associated with PDE10A in the ovarian tumor microenvironment." (PMID 36324187, 2022). "In addition, the molecular profile associated with PDE10A-HIGH expressing ovarian tumors suggests a microenvironment enriched with immune infiltrates, pro-inflammatory cytokines and chemokines, and the activation of many oncogenic signaling pathways." (PMID 36324187, 2022). "First, we identified genes moderately to strongly coexpressed with PDE10A in the TCGA ovarian tumors based on Spearman correlation values provided in the cBioportal." (PMID 36324187, 2022). "A meta-analysis comparison of the gene expression profile observed in the TCGA ovarian tumors expressing high levels of PDE10A with that of SKOV3 PDE10A KO cells revealed a number of genes, pathways, and biological functions overlap." (PMID 36324187, 2022). "Our pathway analysis shows that Wnt and MAPK oncogenic signaling pathways are positively correlated with PDE10A expression as well as many other oncogenic pathways in the TCGA ovarian tumors." (PMID 36324187, 2022). "Clinical specimens obtained from our institutional biobank replicated this finding, showing two times higher PDE10A mRNA levels in normal ovary tissue as compared to ovarian tumors, and downregulation of PDE10A in tumors of 9 out 14 patients with matched normal ovary and ovary tumors." (PMID 36324187, 2022). "Our findings are clinically relevant as they reveal that high expression of PDE10A in ovarian tumors correlates with significantly worse overall survival for patients and with upregulation of various oncogenic pathways, including Wnt and MAPK signaling, in the tumor microenvironment." (PMID 36324187, 2022). "However, PDE10A upregulation was observed in some patient ovary tumors." (PMID 36324187, 2022).
paraneoplastic neurological syndrome (1 paper, 2025). "Beyond solid tumors, paraneoplastic neurological syndromes (PNS) have been associated with anti-PDE10A IgG antibodies." (PMID 41179677, 2025). "introduces a novel autoantibody, PDE10A IgG, as a biomarker for a rare paraneoplastic neurological syndrome that affects older adults with cancer (particularly lung, renal, and pancreatic carcinomas) and is characterized by hyperkinetic movement disorders." (PMID 41179677, 2025).
proteinopathy (1 paper, 2020). "Our review shows that multiple new tracers have been developed for proteinopathy targets, particularly tau, as well as the purinoceptor P2X7, phosphodiesterase enzyme PDE10A, and synaptic vesicle glycoprotein 2A (SV2A), amongst others." (PMID 31541283, 2020).
rectal tumor (1 paper, 2020). "Conversely, it downregulated EEF1A2 in normal rectum organoids, PDE10A in normal colon organoids, and TGFB1 in rectal tumor organoids." (PMID 32824266, 2020).
sarcoma (1 paper, 2025). A usually aggressive malignant neoplasm of the soft tissue or bone. "Additionally, PDE10A::BRAF fusions have been reported in rare pediatric sarcomas." (PMID 41179677, 2025). "-An ETV6-NTRK3 fusion-negative spindleCell sarcoma with IFS-like morphology, subjected to genomic profiling, revealed a PDE10A-BRAF fusion." (PMID 41179677, 2025).
temporal lobe epilepsy (1 paper, 2017). A localization-related (focal) form of epilepsy characterized by recurrent seizures that arise from foci within the temporal lobe, most commonly from its mesial aspect. "PDE10A was primarily located in neurons, and PDE10A expression increased significantly in patients with temporal lobe epilepsy." (PMID 28439226, 2017).
thyroid diseases (1 paper, 2026). "Meanwhile, through cross-tissue TWAS and multi-omics integration, we for the first time reveal the potential roles of FAM227B and PDE10A in thyroid diseases." (PMID 41570039, 2026).
Tics (1 paper, 2024). Repeated, individually recognizable, intermittent movements or movement fragments that are almost always briefly suppressible and are usually associated with awareness of an urge to perform the movement. "Insofar as tics in TS are triggered by an aberrant reward drive to release a tic, this effect of PDE10A inhibition, if mechanism rather than drug specific, may contribute a unique component to efficacy in addition to the more direct suppression of tic release." (PMID 39056811, 2024).
tumor (33 papers, 2015 to 2026). "In prostate cancer (PCa), somatic mutations in PDE10A are restricted to tumor tissues and have lower expression in regular counterparts." (PMID 41179677, 2025). "Combined CRISPR/Cas9 data, human spatial transcriptomic data, and human and mouse RNA sequencing data led to the nomination of PDE10A as a potential haploinsufficient tumor suppressor in the 6q27 region." (PMID 41179677, 2025). "Pharmacological inhibition of PDE10A using selective inhibitors has demonstrated potent anti-tumor effects in preclinical models by restoring cyclic nucleotide levels and suppressing oncogenic signaling." (PMID 41179677, 2025). "Loss of PDE10A in GBM correlates with poor prognosis and aggressive tumor phenotypes across multiple GBM cohorts." (PMID 41179677, 2025). "Critically, the anti-tumor efficacy of PDE10A inhibitors like PF-2545920 and MCI-030 occurs at concentrations that significantly elevate cyclic nucleotides without immediately activating PI3K/AKT feedback loops in responsive tumors." (PMID 41179677, 2025). "In GBM, PDE10A has been identified as a haploinsufficient tumor suppressor located at chromosomal locus 6q27." (PMID 41179677, 2025). "PDE10A appears to act as either a tumor suppressor or an oncogene based on tissue type and the surrounding tumor microenvironment." (PMID 41179677, 2025). "This functional specificity likely reflects a tumor-context preference for cGMP regulation mediated by PDE10A." (PMID 41179677, 2025). "These contain known cancer-testis antigen genes (MEGA5, MEGA1, TEX15, PNMA5 and ROR1) and a number of new candidate genes (PAX2, NTN4, NTNG2 and PDE10A), these genes can be used as tumour markers or potential therapeutic targets with some clinical value." (PMID 37994961, 2023). "The overall tumor burden of nude mice injected intraperitoneally with PDE10A KO cell lines was significantly reduced compared to vector control." (PMID 36324187, 2022). "Recent studies showed that PDE10A expression is upregulated in certain cancer models suggesting that PDE10A-mediated signaling is involved in tumor cell growth." (PMID 31853617, 2020). "By comparing malignant and non‐malignant epithelial cells in PSC, malignant cells showed high expression of marker genes associated with epithelial–mesenchymal transition (EMT) and tumour metabolism regulation related genes, such as HMGA2, FN1, PDE10A, and PCAT1." (PMID 41469334, 2026). "Recent studies suggest that PDE10A is overexpressed in specific cancer types and may contribute to tumor progression, making it a potential biomarker and therapeutic target." (PMID 41179677, 2025). "The top-ranked tumor-cell-specific DCI genes were PDE10A and NR4A2 involved in cAMP pathways." (PMID 37433798, 2023). "Expression levels of seven CBX7 targets, namely Wnt10a, Ccne1, Fgfr2, Bhlhe22, Klhdc8a, Pde10a, and Dusp4, which had been significantly inhibited in miR-181ab1 KO compared to WT tumours in mice, were also significantly lower in either iClust2 or iClust3 than iClust1 HCCs." (PMID 35867177, 2022). "It has been suggested that the effects exerted on the vasculature by PPV is a result of the inhibition of PDE10A, which may aid in inhibiting tumor progression." (PMID 36359780, 2022). "High tumor expression of PDE10A correlated with decreased RFS (p = 0.0006) and OS (p = 0.002)." (PMID 29766673, 2018). "In addition, PDE10A exhibits context-dependent roles within tumor biology." (PMID 41179677, 2025). "Accordingly, it also increases the importance of existence and establishing a therapeutic window, describing the dose and period of time of treatment, which may be based on tumor PDE10A expression and PI3K/PTEN status, to maximize efficacy while minimizing the risks of compensatory signaling." (PMID 41179677, 2025). "Since PPV affects the mitochondrial complex I independently from PDE10A inhibition, it is suggested that PPV has more than one target and affects tumor mitochondrial metabolism." (PMID 36359780, 2022).
tumor (continued). "Among them were known cancer/testis antigen genes (PNMA5, SPATA22, ROR1, and CT45A6) and some new candidates (PAX2, HES4, PEG10, NTN4, PDE10A, and POSTN), these genes could be useful tumor markers and potential therapeutic targets." (PMID 30922328, 2019). "Second, we hypothesize that PDE10A is not an oncogenic driver, but rather can impact the tumor microenvironment to drive cancer progression and malignancy." (PMID 36324187, 2022).
cancer (26 papers, 2016 to 2025). A tumor composed of atypical neoplastic, often pleomorphic cells that invade other tissues. "Collectively, these findings highlight the therapeutic potential of PDE10A inhibition in specific cancer types." (PMID 41179677, 2025). "Preclinical studies have consistently demonstrated the antitumor efficacy of PDE10A inhibitors across various cancer models." (PMID 41179677, 2025). "Despite the growing evidence linking PDE10A to cancer biology, most existing reviews focus primarily on its role in neurological disorders, and only limited literature addresses its function in oncogenesis." (PMID 41179677, 2025). "In the context of oxidative stress, the enzyme phosphodiesterase 10A (PDE10A) is elevated in cancer cells, hydrolyzing cAMP and cGMP." (PMID 38398072, 2024). "Recent research suggests that inhibiting Pde10a reduces cancer cell growth and promotes cell cycle arrest and apoptosis by suppressing β-catenin and RAS signals in cancer cells, indicating that Pde10a plays a critical role in cell proliferation." (PMID 37569835, 2023). "In vivo tumorigenicity of SKOV3 PDE10A KO cells was assessed in an athymic nude xenograft mouse model 7 weeks after intraperitoneal implantation of cancer cells, which revealed significantly impaired neoplastic potential of PDE10A KO clones." (PMID 36324187, 2022). "RNA sequencing revealed a suppression of many oncogenic genes in PDE10A KO clones, including pathways in cancer more generally, and the Wnt pathway." (PMID 36324187, 2022). "It was reported that the specific IgG for phosphodiesterase 10A is a biomarker of patients with paraneoplastic neurologic autoimmune syndrome, and of these patients, 5/6 cancers were adenocarcinomas." (PMID 34565447, 2021). "An overview of PDE10A targeted or used as a biomarker in each cancer." (PMID 41179677, 2025). "Therefore, Pharmacological inhibition of PDE10A has emerged as a promising strategy in cancer therapeutics due to its selective overexpression in malignant tissues and minimal expression in corresponding normal cells (6–12,)." (PMID 41179677, 2025). "In summary, PDE10A demonstrates context-specific roles across various cancer types." (PMID 41179677, 2025). "Although the primary aim of this review is to explore PDE10A as a diagnostic and therapeutic target in cancer, we first provide a brief overview of the structural characteristics and oncological relevance of other PDE isoforms to show and compare the dual role and expression of PDE10A in cancers." (PMID 41179677, 2025). "The differential expression of PDE10A and its regulatory influence on oncogenic pathways, such as the PI3K/AKT, MAPK, and β-catenin pathways, underscores its role in cancer progression." (PMID 41179677, 2025). "This could be related to the context-dependent manner of PDE10A inhibition, which modulates cAMP and cGMP levels accordingly, leading to differential activation of PKA and PKG across various cancer models." (PMID 41179677, 2025). "Recent findings suggest that inhibiting PDE10A attenuates DOX-induced cardiotoxicity and prevents cancer growth, and thus could be a promising strategy in cancer therapy." (PMID 38398072, 2024). "New PDE10A-inhibiting lead compounds that do not cross the blood brain barrier are being developed for cancer treatment (Gary Piazza, South Alabama)." (PMID 31853617, 2020). "In addition, overexpression of PDE10A in cancer cells and tumors compared to normal cells and normal tissues has been observed." (PMID 41179677, 2025).
movement disorder (13 papers, 2016 to 2025). Neurological conditions resulting in abnormal voluntary or involuntary movement, which may impact the speed, fluency, quality and ease of movement. "Childhood-onset familial chorea cases with PDE10A mutations and PDE10A reduction in HD are the focus of recent studies in the field of movement disorders." (PMID 40943492, 2025). "Biallelic loss‐of‐function variants in PDE1B underlie a novel early‐onset movement disorder resembling the phenotype associated with PDE10A deficiency." (PMID 40492975, 2025). "Intriguingly, human mutations in PDE10A lead to loss of striatal PDE10A and are accompanied by an hyperkinetic movement disorder with onset in infancy, indicating that PDE10A plays a key role in regulating striato-cortical movement control." (PMID 33671541, 2021). "PDE10A has emerged as a central regulator of motor control following the identification of single mutations in the enzyme that lead to hyperkinetic movement disorders." (PMID 31871190, 2020). "Our results show that an aberrant compartmentalization of PDE10A underlies the hyperkinetic movement disorders observed in individuals carrying mutations in this gene." (PMID 31871190, 2020). "Both heterozygous and bi-allelic mutations in PDE10A cause childhood-onset chorea, suggesting that PDE10A deficiency and consequent cAMP dysregulation might contribute to the pathogenesis of movement disorders." (PMID 40943492, 2025). "Furthermore, mutations in several PDE genes, including PDE8B,7, 8, 9, 10PDE2A,11, 12 and PDE10A,13, 14, 15, 16, 17, 18 underlie rare genetic diseases manifested mainly by movement disorders." (PMID 40492975, 2025). "Additionally, [11C]31 PET studies indicated that homozygous or heterozygous mutations in the PDE10A gene are linked with dysregulation and pathological reduced striatal expression of the enzyme that might lead to the progression of movement disorders." (PMID 33917199, 2021). "However, surprisingly, these mice showed a clear hypokinetic movement disorder, suggesting that the same reduction in PDE10A activity results in radically opposite effects on movement production in humans and mice." (PMID 34155691, 2021).
neurodegenerative disease (7 papers, 2016 to 2023). A disorder of the central nervous system characterized by gradual and progressive loss of neural tissue and neurologic function. "In contrast to GAF-A mutants, dominant mutations in the GAF-B domain of PDE10A induce PDE10A misfolding, a common pathological phenotype in many neurodegenerative diseases." (PMID 31871190, 2020). "As protein inclusions or their intermediate species have repeatedly been associated with the cytotoxicity that underlies cell death in many neurodegenerative diseases, we next evaluated the effect of PDE10A aggregates on cellular survival using the xCELLigence system." (PMID 31871190, 2020). "Phosphodiesterase type 10A (PDE10A) is highly enriched in striatum and is under evaluation as a drug target for several psychiatric/neurodegenerative diseases." (PMID 27247380, 2016). "Thus multi-target ligands that bind to different adenosine receptors subtypes (A1 and A2A receptors) while simultaneously inhibit PDE10A might be synergistic in modulating cAMP levels, which is of therapeutic potential for neurodegenerative diseases." (PMID 29290010, 2017).